ARG1 (arginase 1)
Diseases named in the same sentence as ARG1 in open-access papers (continued):
Sharing a sentence is not in itself a finding about the gene and the disease.
metabolic disease (10 papers, 2019 to 2025). A congenital disorder (due to inherited enzyme abnormality) or acquired (due to failure of a metabolically important organ) disorder resulting from an abnormal metabolic process. "Arginase 1 Deficiency (ARG1-D; OMIM 207800) is a rare inherited metabolic disorder caused by biallelic pathogenic variants in the ARG1 gene (HGNC 663) impairing enzymatic activity of arginase 1 (ARG1, EC 3.5.3.1), the final step in the urea cycle." (PMID 38292042, 2024). "A final example concerns arginase deficiency, a rare autosomal recessive metabolic disease caused by variants in the arginase 1 (ARG1) gene." (PMID 36678889, 2023). "Arginase 1 Deficiency (ARG1-D) is a rare inherited metabolic disease with progressive, devastating neurological manifestations with early mortality and high unmet need." (PMID 35236361, 2022). "Of these, arginase-1 deficiency is reported in approximately 1 in 2.2 million people and is an extremely rare autosomal recessive metabolic disorder." (PMID 32025996, 2019). "Arginase 1 Deficiency (ARG1-D) is a debilitating and progressive metabolic disease characterized by persistent elevation of arginine and its metabolites, ultimately leading to significant morbidity and early mortality." (PMID 35236361, 2022). "Arginase 1 Deficiency (ARG1-D) is a rare debilitating, progressive, inherited, metabolic disease characterized by marked increases in plasma arginine (pArg) and its metabolites, with increased morbidity, substantial reductions in quality of life, and premature mortality." (PMID 38292042, 2024). "Stimulation of the macrophage cell line RAW264.7 with OSMR results increases the expression of M2 markers (IL-10, Arg1, and CD206), and the loss of OSMR leads to the polarization of adipose tissue macrophages to M1 phenotypes that increase inflammation in a mouse model of metabolic diseases." (PMID 37120549, 2023).
bacterial infection (9 papers, 2013 to 2024). "Interestingly, immune complexes were previously shown to induce a robust FcR- and complement-mediated activation of C/EBPbeta, and C/EBPbeta has previously been associated with Arg1 induction in response to bacterial infection, indicating it may also play a role in our model." (PMID 24244174, 2013). "Furthermore, increased Arg1 activity by Th2 cytokines dampened lung immunity against bacterial infections in mice, suggesting Arg1 blockade as a therapeutic intervention to lower lung infections in asthmatic patients." (PMID 37275910, 2023). "BacSig was defined as the signature of the host response to bacterial infection using the average expression of five representative genes, including S100A12, CD177, HP, ANXA3, and ARG1." (PMID 38790931, 2024).
infectious disease (8 papers, 2017 to 2025). A disorder directly resulting from the presence and activity of a microbial, viral, or parasitic agent in humans. "Since the activity and expression of Arginase-1 are correlated with increased pathogen loads in infectious diseases, we found that ME49Δcdpk3 strain promotes the proliferation of T. gondii more than the ME49 wild-type strain in macrophages." (PMID 40394721, 2025). "ARG1 is expressed by macrophages, and downregulates immunosuppressive cytokine production (e.g., IL-4, IL-5, and IL-13) by T-helper cell 2 (Th2) in response to infectious disease." (PMID 35008799, 2021). "Additionally, some of these target genes, including SOD2, TNFAIP3, ARG1, SERPINB2, VLDLR, HSPA5, and LCN2, are associated with infectious diseases, suggesting that lncRNAs respond to PCV2 infection by regulating these genes." (PMID 30863688, 2019). "In addition, we analyzed the predicted target genes of differentially expressed lncRNAs, including SOD2, TNFAIP3, and ARG1, all of which are involved in infectious diseases." (PMID 30863688, 2019).
neurodegenerative disease (8 papers, 2021 to 2026). A disorder of the central nervous system characterized by gradual and progressive loss of neural tissue and neurologic function. "Arg1 is known to regulate oxidative stress in various degenerative diseases by modulating nitric oxides (NO)." (PMID 40002138, 2025). "Arginase I (Arg1) is a key part of the urea cycle, which is important for metabolic aspects of neuronal pathologies, including neurodegenerative diseases and acute CNS injury." (PMID 41488750, 2025). "Primarily M2 phenotype microglia with high expression of Arginase-1 contribute to axon regeneration through anti-inflammatory effects in neurodegenerative diseases." (PMID 34122007, 2021). "Electroacupuncture enhanced the activations of M2 marker Arginase 1 (Arg1) and Iba1-positive cells in the hippocampus, when used as a treatment for neurodegenerative diseases such as Alzheimier’s disease." (PMID 34830410, 2021). "Nevertheless, the ability of M. vaccae NCTC 11659 to increase Arg1 mRNA expression, as observed now both in vivo and in vitro, may lead to a less aggressive M1-like inflammatory environment, which may be beneficial in some conditions, including neurodegenerative diseases and psychiatric disorders." (PMID 38203645, 2023). "In addition, CDNF supplementation could enhance Arg1 expression in 6-OHDA-siumulated BV2 cell lines, suggesting that CDNF can boost microglial polarization toward anti-inflammatory phenotype serving as a reparative role in neurodegenerative diseases." (PMID 35740467, 2022).
adenocarcinoma (4 papers, 2012 to 2021). A common cancer characterized by the presence of malignant glandular cells. "Importantly, this combination therapy regimen effectively reduced the levels of p‐STAT3, p‐AKT, and immunosuppression marker (ARG‐1 protein) and up‐regulated CD8 expression in adenocarcinoma lesions." (PMID 33283987, 2021). "This high specificity of arginase-1 and HepPar-1 combination because the staining patterns of both immunomarkers in adenocarcinomas were mutually exclusive (i.e. arginase-1 - positive adenocarcinomas always lacked HepPar-1 immunoreactivity and vice versa)." (PMID 23111165, 2012).
lung (4 papers, 2010 to 2024). "ARG2 may serve as a potential predictive biomarker, in addition to ASS1 and OTC, for PEGylated ARG1 treatment in lung SCC." (PMID 30808864, 2019).
retinopathy (4 papers, 2013 to 2025). "Arg-1 has an important role in regulating inflammation and is involved in chronic inflammatory conditions and vascular dysfunction in retinopathy." (PMID 23977372, 2013).
benign tumors (2 papers, 2023 to 2024). "Overall, these results reveal that Arg1+ macrophages are monocyte-derived and are specified early after monocyte recruitment to the ischemic heart." (PMID 39433910, 2024). "Moreover, we detected the expression of INOS, IDO and Arg-1 by ELISA in the peripheral blood serum of patients with malignant or benign tumors, which are immunosuppressive factors secreted by MDSCs." (PMID 35725835, 2023).
blood cancer (2 papers, 2020 to 2023). "Indeed, ARG-1 displays a negative effect on immunity in several contexts, including hematological neoplasms: by depleting the microenvironment of arginine, which is essential for T-lymphocyte function, arginase makes them anergic." (PMID 33014780, 2020).
CNS tumors (2 papers, 2021 to 2024). "OAT-1746 inhibited ARG1/2 at low nanomolar concentrations, reversed ARG1-inhibited proliferation of human and murine T cells and showed significant antitumor efficacy in various non-CNS tumor models." (PMID 34504786, 2021).
head and neck tumor (2 papers, 2021). "Aggregated results from one previous report hinted that ARG1 protein expression was higher in head and neck tumor tissues compared with nontumor." (PMID 34885177, 2021).
immune disorders (2 papers, 2016 to 2021). "We hypothesized that increased ARG1 expression is associated with greater AIS severity and immune dysfunction, as measured by an increased NLR." (PMID 26515089, 2016).
genetic disorder (1 paper, 2017). "The focus of this work relates to basic investigations into developing a gene repair strategy for a rare genetic disorder such as Arg1 deficiency, so as to halt progression of the disease." (PMID 28566761, 2017).
inborn errors of metabolism (1 paper, 2015). An inherited disorder resulting from an enzyme defect in biochemical and metabolic pathways affecting proteins, fats, carbohydrates metabolism or organelle function. "At two of the six newly identified loci (6q23, ARG1 and 21q22, HLCS), rare variants are known to cause autosomal recessive inborn errors of metabolism, providing a strong biological plausibility for the SNP-metabolite associations." (PMID 26401656, 2015).
inflammatory myopathies (1 paper, 2025). "In inflammatory myopathies, myeloid-derived suppressor cells (MDSCs)—comprising monocytes and polymorphonuclear cells—co-expressing PD-L1 and arginase-1 were associated with disease progression." (PMID 40621456, 2025). "Interestingly, previous studies in HIV-1-infected patients and inflammatory myopathies have reported PD-L1+/arginase-1+ neutrophils." (PMID 40621456, 2025).
neurodevelopmental disorder (1 paper, 2022). A behavioral and cognitive disorder with onset during the developmental period that involves impaired or aberrant development of intellectual, motor, or social functions. "ARG1 deficiency can lead to seizures, neurodevelopmental disorders, etc.." (PMID 36193133, 2022).
vascular disorder (1 paper, 2021). A general term used to describe any disease affecting blood vessels]. "It seems that the activation of immunosuppressive cells can disturb the balance between the activities of ARG1 and NOS enzymes and subsequently this can lead to vascular disorders." (PMID 33025106, 2021).
ARG1 also shares sentences with these, for which no sentence is quoted: hyperlipidemia (4 papers); idiopathic pulmonary fibrosis (4); bronchopulmonary dysplasia (3); Hodgkins lymphoma (3); lymphopenia (3); non-alcoholic steatohepatitis (3); paroxysmal nocturnal hemoglobinuria (3); acute myocardial infarction (2); amoebiasis (2); beta thalassemia (2); brain cancer (2); cervical cancer (2); chronic obstructive pulmonary disease (2); chronic periodontitis (2); Cryptococcal meningitis (2); developmental delay (2); erectile dysfunction (2); heart disease (2); hereditary spastic paraplegia (2); Hyperornithinemia (2); Intellectual disability (2); neuroendocrine tumors (2); Ornithine transcarbamylase deficiency (2); renal carcinoma (2); renal cell carcinoma (2); schizophrenia (2); skin infection (2); abdominal aortic aneurysm (1); acute lung injury (1); AIDS (1).
A further 85 diseases each share a sentence with ARG1 in 1 paper.